FEN1 (flap structure-specific endonuclease 1)
Diseases named in the same sentence as FEN1 in open-access papers (continued):
Sharing a sentence is not in itself a finding about the gene and the disease.
tumor (continued). "The involvement of FEN1, ZBTB3, and MTA2 in controlling genomic stability suggests that functional dysregulation of these genes through mutations would facilitate further tumor mutagenesis, raising the possibility of these oncogenes as potential therapeutic targets for ESCC patients." (PMID 29348864, 2017). "When cisplatin was combined with the FEN1 inhibitor, the tumor growth was significantly reduced." (PMID 28371273, 2017). "However, it also raises some questions, including how FEN1 is secreted into the extracellular space or serum, if serum FEN1 levels are related to intracellular FEN1 levels and whether FEN1 is a tumor-specific marker." (PMID 34277392, 2021). "Therefore, FEN1 has been considered as a new tumor marker in recent year s." (PMID 32586310, 2020). "This process overcomes FEN1-mediated immunosuppression, promoting CD8+ T cell-mediated anti-tumor activity through cell cycle arrest and apoptosis of tumor cells." (PMID 40486875, 2025). "A heatmap of the 11 mRNA expression levels of the tumor samples displayed that the seven genes, including CCNB1, CCNB2, CHEK1, FEN1, PTTG1, RACGAP1, and UBE2C, had higher expression levels in the tumor tissue." (PMID 41009526, 2025). "We further studied the effect of AR knockdown on AR, FEN1, pho‐ERK1/2 and pho‐ELK1 expression in tumour tissues by Western blot." (PMID 37326412, 2023). "The expressions of FEN1 and TCF3 were mainly enriched in pit mucous and grand mucous cells, while SERPINE1 was mainly expressed in tumor cells." (PMID 37100457, 2023). "AR knockdown statistically significantly decreased FEN1, pho‐ERK1/2 and pho‐ELK1 expression in tumour tissues of nude mice as compared with the 22Rv1‐control group (all p < 0.001)." (PMID 37326412, 2023). "Tumor cells in chemo-resistant samples showed higher expression of chemoresistance and proliferation related genes (FN1, LCN2, CD44, FEN1)." (PMID 36248860, 2022). "Other key repair genes such as FEN-1, LIG1, XPA and TOP3A were also found downregulated indicating reduced tumor progression, chemo-resistance, alternative end-joining (Alt-EJ) and nucleotide excision repair (NER)." (PMID 34680264, 2021). "Furthermore, inhibition of FEN1 expression could improve the anti-tumor effect of ROS inducer ATO." (PMID 32318339, 2020). "A review of the literature found that six of the 12 upregulated genes (KPNA2, CDK1, TARBP1, PRC1, FEN1, and MCM6) were overexpressed in HCC tissue compared to levels in non-tumor tissue based on immunohistochemical staining." (PMID 32213663, 2020). "However, it is not clear whether FEN1 deficiency can affect the ROS levels in tumor cells, high expression of FEN1 might effectively repair the oxidative damage, leading to drug resistance in TNBC cells." (PMID 32318339, 2020). "FEN1 promotes HCC cell migration, invasion in vitro and promotes tumor growth and lung metastasis in vivo." (PMID 32213663, 2020). "We demonstrated that FEN1 silencing inhibits HCC cell epithelial-mesenchymal transition (EMT), invasion and migration in vitro and significantly suppressed tumor growth and metastasis in vivo." (PMID 31402791, 2019). "FEN1 promoted HCC cell migration and invasion through inhibiting EMT in vitro, and accelerated xenograft tumor growth and lung metastasis in vivo." (PMID 31402791, 2019). "In this study, we demonstrated that FEN1 silencing inhibited HCC cell migration, invasion and EMT in vitro, and inhibited tumor growth and lung metastasis in vivo." (PMID 31402791, 2019). "The results showed that FEN1 is primarily localized in the nucleus and that FEN1 expression significantly increased in HCC tissue compared to the adjacent para-tumor tissues." (PMID 31402791, 2019). "Next, we assessed protein expression levels by immunohistochemistry for MLH1, MPG, FEN1, Polβ and XRCC1 in tumour vs. healthy tissue of this patient cohort." (PMID 28903334, 2017).
tumor (continued). "Since FEN1 plays important roles in long‐patch BER and Okazaki fragment maturation, it could substantially attenuate the anti‐tumour effects of DNA damaging agents, such as cisplatin and DTX." (PMID 37326412, 2023). "From day 13 to day 28, the tumor volume after FEN1 knockdown was significantly smaller than that in the controls, and the tumor proliferation was not obvious in the whole process." (PMID 37185662, 2023). "Then, the tumor was dissected and IHC was performed, the results showed that the volume of cell nuclei in controls significantly increased, and PCNA was expressed in most cells in controls and was significantly higher than that in FEN1-shRNA group." (PMID 37185662, 2023). "Time-dependent increased RAD51, FEN1 and UNG expression levels were confirmed after LPS stimulation, which may contribute to tumor cell fitness." (PMID 33446690, 2021). "Additionally, the results were compared with known tumor markers (CA153 and CEA) to determine the potential significance of FEN1." (PMID 34277392, 2021). "Therefore, we first utilized the ONCOMINE and FIREBROWSE online databases to investigate the expression of FEN1 in HCC, and found that FEN1 was highly expressed in multiple tumor tissues including those of HCC patients, consistent with previous reports." (PMID 31534853, 2019). "Under the same conditions, the transplantation of A549 cells with FEN1 knockdown into nude mice did not lead to tumor formation (data not shown)." (PMID 28371273, 2017). "By using multivariate Cox proportional hazards models with backward stepwise exclusion, XRCC1 (p = 0.002), FEN1 (p = 0.001), pol β (p = 0.032), BRCA1 (p = 0.040) and tumour stage (p < 0.0001) remained significant independent predictors for BCSS after controlling for adjuvant chemotherapy." (PMID 26267318, 2015). "Of note, previous studies identified that Wdr4 exerts multiple functions, such as regulating tumor microenvironments, stabilizing tRNA, and maintaining genome stability, through interacting with different partners/effectors, including DDB1/PML, METTL1, and FEN1, individually." (PMID 36681682, 2023). "In addition, flow cytometry results demonstrated that AR knockdown induced increased apoptosis and G1/S phase arrest in tumour cells treated with DTX in vivo.Conversely, FEN1 overexpression reversed apoptosis and G1/S phase arrest induced by DTX and AR knockdown." (PMID 37326412, 2023). "The following study investigated whether the inhibition of Flap Endonuclease 1 (FEN1) expression, the key enzyme in the base excision repair (BER) pathway, could improve the anti-tumor effect of arsenic trioxide (ATO), which is a reactive oxygen species (ROS) inducer." (PMID 32318339, 2020). "FEN1 levels were not correlated with gender, age, race, or tumor grade." (PMID 32399086, 2020). "But whether high expression level of FEN1 would influence tumor progression was still not clear." (PMID 28371273, 2017). "In primary HGSOC, the recurrent tumor-specific DEG IL7R exhibited a positive correlation with AMBP and HDGF and a negative correlation with FEN1, LRRC25, RIGI, and TBL1X (p < 0.05)." (PMID 41596598, 2026). "For instance, in “DPD →Final”, there is a significant synergism between the not-regulated FEN1 and REC1 in the PTC nodule of the tumor ((COR = 0.978;), but also between the up-regulated FEN1 and the down-regulated REC1 in the BCPAP cells (COR = 0.951)." (PMID 38790250, 2024). "Out of 11 genes associated with the non-homologous end joining, 4 (i.e., XRCC4, PRKDC, FEN1, and DCLRE1C) display significantly higher expressions in OS tumor samples than normal controls while DNTT has no detectable expression in normal controls." (PMID 35013466, 2022).
infection (12 papers, 2016 to 2025). The state of being infected such as from the introduction of a foreign agent such as serum, vaccine, antigenic substance or organism. "Fiber quantification showed that FEN1 inhibitor-induced ssDNA gaps could be readily detected by the spreading assay following infection using both wild type and integrase-deficient lentiviruses." (PMID 41510250, 2025). "Unexpectedly, however, when FEN1 was silenced in U2OS cells via lentiviral infection of shRNAs four days prior to DNA spreading, the gaps were readily detectable." (PMID 41510250, 2025). "To directly analyze the role of FEN1 during host colonization and infection, we deleted the FEN1 ORF and colonized mice with fen1Δ and fen1-W145* (GI-240)." (PMID 39250486, 2024). "For this, we infected HFFs with the HCMV strain AD169 at a MOI of 3 and analyzed endogenous FEN1 protein levels at different time points post infection by Western blotting." (PMID 33770148, 2021). "Experiments with a recombinant virus strain lacking IE1 revealed that IE1 is even necessary for the upregulation of FEN1 at the initial phase of infection." (PMID 33770148, 2021). "These experiments clearly demonstrate that IE1 mediates an accumulation of phosphorylated FEN1 in transfection and infection experiments." (PMID 33770148, 2021). "Surprisingly, we found FEN1, which displays a pan-nuclear staining pattern in uninfected cells, to be excluded from the nucleolus starting with the immediate-early phase of infection." (PMID 33770148, 2021). "In our infection system, CagA expression was observed to promote decrease of FEN1, thereby potentially favoring genomic instability." (PMID 33339161, 2020). "Recently, FEN1, a single strand DNA repair component, had been shown to be required for cccDNA synthesis via both de novo infection and intracellular amplification pathways, most likely by processing the 5’ flapped structure presented in rcDNA." (PMID 31026293, 2019). "Infection experiments showed that inhibition of FEN1 activity reduced HBV DNA secretion in NTCP-expressing cells and primary human hepatocytes." (PMID 29928064, 2018). "A complex consisting of IE1 and FEN1 could be detected starting at 8 hours post infection (hpi) (first panel, lanes 6 to 10)." (PMID 33770148, 2021). "Infection experiments utilizing an siRNA directed against E2F1 could show that E2F1 contributes to the upregulation of FEN1 suggesting a regulation at the transcriptional level." (PMID 33770148, 2021). "Interestingly, similar results were obtained when applying the FEN1 inhibitor PTPD during AD169 infection." (PMID 33770148, 2021). "Therefore, infection-induced FEN1 decrease could also be a contributing factor to telomere loss and chromosomal instability." (PMID 33339161, 2020). "Consistent with its potential role in DDR during infection, our previously published SIRT2 interactome identified many DNA damage sensor and repair proteins including KU70/KU80, RPA1, FEN1 and PARP1." (PMID 34929015, 2021). "To further investigate the observed exclusion of FEN1, we again infected HFFs mCherryFEN1 with AD169 and analyzed earlier time points reflecting the immediate-early phase of infection." (PMID 33770148, 2021). "The protein levels of NTHL1, MUTYH, FEN1, RAD51, POLD1, and LIG1 were observed to be decreased, during the infection, in a CagA- and phospho-CagA-related manner in both cell lines." (PMID 33339161, 2020). "Our study showed that infection can promote an imbalance between APE1 and the downstream proteins of LP-BER FEN1, POLD1, and LIG1." (PMID 33339161, 2020). "Most importantly, FEN1 and PNKP were also highly expressed inside the gut of silkworms post infection, in contrast SWP4 was down regulated." (PMID 27708628, 2016). "Furthermore, several host cellular DNA repair proteins, such as tyrosyl-DNA phosphodiesterase 2 (TDP2), DNA polymerase (Pol), flap endonuclease 1 (FEN1), and DNA ligases, are required for cccDNA synthesis in de novo infection and intracellular amplification." (PMID 34931766, 2021).
infection (continued). "The delay of HCMV growth on cells lacking FEN1 was further demonstrated to depend on the multiplicity of infection (MOI) showing the highest requirement for FEN1 at low MOI conditions." (PMID 33770148, 2021). "In order to analyze whether HCMV alters the localization of FEN1, mCherryFEN1 cells were infected with AD169 and examined via indirect immunofluorescence utilizing UL44 as marker for infection." (PMID 33770148, 2021). "Interestingly, upon AD169 infection, all cells infected with HCMV displayed a changed FEN1 staining pattern: FEN1 was observed to be excluded from a subnuclear structure (marked by arrowheads), which presumably corresponds to the nucleolus." (PMID 33770148, 2021). "According to the AD169 infection, we could again detect an HCMV-mediated upregulation of FEN1 starting at 24 hpi." (PMID 33770148, 2021). "Comparative analyses between an HCMV wildtype strain and a recombinant mutant strain lacking IE1 confirmed our hypothesis, as we could not detect FEN1 phosphorylation during infection with the IE1-deleted virus." (PMID 33770148, 2021). "Western Blot analyses clearly revealed that IE1 is required for the accumulation of phosphorylated FEN1, as we could not detect pFEN1 during infection with the IE1-deleted virus (first panel, compare lanes 1 and 3 with 2 and 4)." (PMID 33770148, 2021).
adenocarcinoma (4 papers, 2009 to 2015). A common cancer characterized by the presence of malignant glandular cells. "Functional pathways analysis using the IPA® software revealed significant modulation of neighborhood and network gene modules surrounding the Mcm2 and Fen1 genes in the Gprc5a−/− adenocarcinoma (top and bottom, respectively)." (PMID 20686609, 2010). "A key feature of the signature, up-regulation of Ube2c, Mcm2, and Fen1, was validated in mouse normal lung and adenocarcinoma tissues and cells by immunohistochemistry and western blotting, respectively." (PMID 20686609, 2010). "Because gene expression at the mRNA level does not always correspond to protein levels, we then examined the expression of the protein products of Ube2c, Fen1 and Mcm2 in Gprc5a−/− lung normal and adenocarcinoma tissue and cells." (PMID 20686609, 2010). "Using comparative functional genomics and functional pathways analysis followed by validation at the protein level by immunohistochemistry and western blotting analyses, we highlighted the marked up-regulation of Ube2c, Mcm2 and Fen1 in Gprc5a-knockout mouse adenocarcinoma relative to normal lung." (PMID 20686609, 2010). "In accordance, Mcm2, Fen1, Ube2c and cyclin D1 proteins were also relatively higher in the MDA-F471 mouse adenocarcinoma cells compared to the normal Gprc5a−/− cells as revealed by the western blotting analysis." (PMID 20686609, 2010).
colon (3 papers, 2021 to 2022). "Interestingly, the downregulated DEGs, such as MAD2L1, CCNA2, MCM2, MCM4, FEN1, and CDK6, were enriched in DNA replication, tyrosine metabolism, and cell cycle pathways, which are commonly upregulated in colon cancer." (PMID 34521988, 2021).
genetic diseases (3 papers, 2014 to 2018). "Mutations that reduce FEN1 expression or alter its activity are linked to cancers and genetic diseases." (PMID 28230529, 2017). "The functional deficiency of FEN1 may lead to severe genomic instability and an increased mutation rate, contributing to susceptibility to a number of genetic diseases." (PMID 25153632, 2014). "This could increase our understanding of how problems with FEN1 and similar proteins lead to different genetic diseases." (PMID 28230529, 2017).
FEN1 also shares sentences with these, for which no sentence is quoted: non-small cell lung carcinoma (4 papers); acute myeloid leukemia (1); Alzheimer disease (1); Arthritis (1); Astigmatism (1); astrocytomas (1); autoimmune disease (1); bladder cancer (1); bladder urothelial carcinoma (1); bubonic plague (1); cardiomyopathy (1); cholangiocarcinoma (1); chronic obstructive pulmonary disease (1); Cognitive impairment (1); colon adenocarcinoma (1); colorectal adenocarcinoma (1); Endothelial Corneal Dystrophy (1); ependymoma (1); epilepsy (1); esophageal carcinoma (1); hepatitis B infection (1); HIV-1 infection (1); Hydrocephalus (1); Hypertension (1); immune diseases (1); leiomyoma (1); liver (1); lymphoma (1); meningeal tumours (1); metastatic prostate carcinoma (1).
A further 16 diseases each share a sentence with FEN1 in 1 paper.